TPH2 (tryptophan hydroxylase 2)
Diseases named in the same sentence as TPH2 in open-access papers (continued):
Sharing a sentence is not in itself a finding about the gene and the disease.
Stroke (2 papers, 2018 to 2019). Sudden impairment of blood flow to a part of the brain due to occlusion or rupture of an artery to the brain. "The C/C-G/T, C/A-G/T and A/A-G/T combined genotypes of c.-1849C>A – IDO1 (rs3824259) and c.-844G > T – TPH2 (rs4570625) caused a reduction of the stroke risk in the Polish population." (PMID 31817010, 2019). "On the one hand, we observed that the G/C-G/G combined genotype of the c.-1493G > C – IDO1 (rs10089084) and c.-844G > T – TPH2 (rs4570625) polymorphisms were associated with an increased risk of stroke." (PMID 31817010, 2019). "In the case of c.803 + 221C > A – TPH1 (rs1800532) and c.-844G > T – TPH2 (rs4570625), the C/C-G/G and C/A-G/G were linked with the risk of stroke elevated by more than 10 times (p < 0.001)." (PMID 31817010, 2019). "We found that the C/C-G/G combined genotype of the c.804-7C>A – TPH1 (rs1799913) and c.-844G > T – TPH2 (rs4570625) polymorphisms were associated with an increased risk of stroke." (PMID 31817010, 2019). "In case of combined polymorphisms encoding TPH2 – i.e., c.-1449C > A (rs7963803) and c.-844G > T (rs4570625) – the CG increased the risk of stroke, while the CT, AG and AT haplotypes reduced this risk." (PMID 31817010, 2019). "In case of c.-1449C > A – TPH2 (rs7963803), the C/C genotype and the C allele were positively correlated with stroke occurrence, whereas the heterozygote and the A allele protected against the onset of stroke." (PMID 31817010, 2019). "Moreover, we observed that the C/C-C/C combined genotype of the c.803 + 221C > A – TPH1 (rs1800532) and c.-1449C > A – TPH2 (rs7963803) polymorphisms were associated with an increased risk of stroke, whereas the C/A-C/A genotypes reduced the risk." (PMID 31817010, 2019). "The G/G-C/C, G/A-C/C combined genotypes of c.*456G>A (rs10988134) – KAT1 and c.-1449C > A – TPH2 (rs7963803) were linked with elevated occurrence of stroke, while the G/G-C/A genotype of the same polymorphism combination decreased this risk more than thirty times (p < 0.001)." (PMID 31817010, 2019). "Interestingly, the presence of the T/T-G/G and C/C-G/G combined genotypes of the c.975-7T > C– KAT2 (rs1480544) and c.-844G>T – TPH2 (rs4570625) polymorphisms elevated the risk of stroke development more than 30 times (p = 0.001)." (PMID 31817010, 2019). "Moreover, we found that the T/T-C/C genotype of c.-173A > T – TPH1 (rs10488682) and c.-1449C > A – TPH2 (rs7963803) was linked with an elevated risk of stroke development, whereas the A/T-C/A genotype caused a decrease of this risk by nearly fifteen times." (PMID 31817010, 2019). "Moreover, the G/G-G/G combined genotypes of c.*456G > A (rs10988134) – KAT1 and c.-844G > T – TPH2 (rs4570625) caused a more than elevenfold increase of the risk in the Polish population (p < 0.001), whereas the G/G-G/T and G/A-G/T genotypes caused a reduction of stroke occurrence." (PMID 31817010, 2019). "There was a link between an increased risk of stroke and the frequency of the C/C-C/C, A/A-C/C genotypes of c.804-7C > A – TPH1 (rs1799913) and c.-1449C > A – TPH2 (rs7963803), while the C/A-C/C and A/A-C/A genotypes reduced this risk." (PMID 31817010, 2019). "In our study, we confirmed the link between a reduced risk of stroke and the frequency of the C/C-C/C genotype of the c.-1493G>C – IDO1 (rs10089084) and c.-1449C > A – TPH2 (rs7963803) polymorphisms." (PMID 31817010, 2019). "Genotyping of TPH2 rs4641528 and rs10879355 was performed from genomic DNA of 383 stroke patients collected previously and stored at −70°C." (PMID 29484259, 2018). "Moreover, the frequency of the C/C-C/A genotype of c.-1849C > A – IDO1 (rs3824259) and c.-1449C>A - TPH2 (rs7963803) was decreased, while the C/A-C/C genotype was increased in the patients after a stroke as compared to the healthy volunteers." (PMID 31817010, 2019). "Our findings suggest that the TPH2 rs4641528 C allele may play a role in the pathogenesis of PSD and PSEI but not PSAP in Korean stroke patients." (PMID 29484259, 2018).
Stroke (continued). "Therefore, it is likely that TPH2 rs4641528 is an important SNP representing other SNPs related to emotional dysfunction not just in stroke patients but also in other psychiatric patients in different ethnic populations." (PMID 29484259, 2018).
sudden infant death syndrome (2 papers, 2020 to 2021). Unexpected death in infancy which remains unexplained following autopsy, review of the medical history, and investigation of the death circumstances and death scene. "Infants that succumb to sudden infant death syndrome (SIDS) have reduced brainstem 5‐HT levels and Tryptophan hydroxylase 2 (Tph2)." (PMID 34228894, 2021). "Broadbelt at al. focused on hypothesis suggesting proteomics might unveil unknown abnormal protein concentrations related to tryptophan hydroxylase (TPH2) and serotonin (5-HT) regulation in sudden infant death syndrome (SIDS) cases using an MS-based proteomic strategy." (PMID 32283897, 2020).
allergic asthma (1 paper, 2024). A asthma with a basis in a pathological type I hypersensitivity reaction. "Further analysis showed increased Tph2, Tph17, Tfh2 and Tfh17 subtypes while decreased Tph1 and Tfh1 subtypes in children with allergic asthma." (PMID 38424520, 2024). "In the current study, we observed increased frequency of CXCR5− Tph, CXCR5−ICOS+ Tph, CXCR5−ICOS+PD-1+ Tph, Tph2 and Tph17 subtypes in children with allergic asthma." (PMID 38424520, 2024). "Then, we further analyzed three Tph subtypes and found a lower frequency of Tph1 subtypes while a higher frequency of Tph2 and Tph17 subtypes in children with allergic asthma than those of HC." (PMID 38424520, 2024). "As expected, the frequency of CD27+CD38+ plasmablasts, CD24hiCD38hi transitional B cells, CXCR5− Tph, CXCR5−ICOS+PD-1+ Tph, Tph2 subtypes and Tfh2 subtypes were weak positively correlated with serum total IgE level in children with allergic asthma." (PMID 38424520, 2024). "Our observations suggest CD24hiCD38hi transitional B cells, CD24hiCD27+ B cells, CXCR5−ICOS+PD-1+ Tph and Tph2 subtypes indreased in children with allergic asthma." (PMID 38424520, 2024). "In summary, it has become clear that the increased CD24hiCD38hi transitional B cell, CXCR5−ICOS+PD-1+ Tph, Tph2 and Tfh2 subtypes may contribute to the development of aberrant immune responses in children with allergic asthma." (PMID 38424520, 2024). "In all, our findings indicate that skewed polarization of Tph2, Tph17, Tfh2 and Tfh17 subtypes may be a factor in the exaggerating immune response of allergic asthma." (PMID 38424520, 2024). "Most interestingly, CXCR5− Tph, CXCR5−ICOS+PD-1+ Tph and Tph2 subtypes were weakly positively correlated with serum total IgE level, suggesting that CXCR5− Tph, CXCR5−ICOS+PD-1+ Tph and Tph2 subtypes may play an important role in the excessive accumulation of serum total IgE in allergic asthma." (PMID 38424520, 2024).
Apnea (1 paper, 2024). Lack of breathing with no movement of the respiratory muscles and no exchange of air in the lungs. "During REM sleep, Tph2−/− mice displayed similar apnea frequency and duration to Tph2+/+ mice." (PMID 38338762, 2024).
astrocytoma (1 paper, 2025). "Further, treatment of human brain glioblastoma/astrocytoma (U87 MG) cells with 1,25(OH)D, the active metabolite of vitamin D, was found to significantly increase TPH2 mRNA in a dose-dependent manner." (PMID 41341996, 2025).
behavioral disorders (1 paper, 2023). "Therefore, our negative result indicates that intraperitoneal BH4 administration cannot increase TPH2 activity, 5-HT levels and metabolism or correct the behavioral disorder caused by low TPH2 activity due to an extremely low level of drug penetration in the brain." (PMID 37892138, 2023). "Single functional amino acid substitutions in mouse TPH2 molecules decreasing the enzyme activity seem to be promising instruments for modeling of the in vitro and in vivo effects of BH4 treatment on the enzyme, as well as behavioral disorders caused by Tph2 gene mutations." (PMID 37892138, 2023).
cleft palate (1 paper, 2021). Cleft palate is a fissure type embryopathy that affects the soft and hard palate to varying degrees. "Additionally, probability of dysphagia was also identified in Rdh10 mutant mice with cleft palate due to retinoid deficiency, TPH2 knockout (TPH-/-) mice with serotonin (5-hydroxytryptamine [5-HT]) deficiency, and Uch-L1gad/Uch-L3Δ3–7 double homozygous mice used as a neuro-degenerative animal model." (PMID 34067192, 2021).
cognitive decline (1 paper, 2021). "Recently, some studies have shown that central ACE2 and TPH2 are involved in pain persistence and cognitive decline." (PMID 34394341, 2021).
colon cancer (1 paper, 2019). "We performed IHC for TDO2, TPH1, AHR, serotonin, and TPH2 in paraffin-embedded patient-derived normal and colon cancer tissues to confirm our TCGA results." (PMID 31416966, 2019).
colorectal tumors (1 paper, 2022). "Furthermore, TPH2+ cells were enriched close to the tumors in human colorectal tumors, and Tph2+ cells were enriched in the “tumor root region” where the tumor originated in mouse CRC tissues." (PMID 36408175, 2022). "Results showed that TPH1 mRNA was lower while TPH2 mRNA was increased in colorectal tumors than in non-tumor tissue." (PMID 36408175, 2022).
delirium (1 paper, 2023). A disorder characterized by confusion; inattentiveness; disorientation; illusions; hallucinations; agitation; and in some instances autonomic nervous system overactivity. "Therefore, we speculate that the lncRNA AABR07042999.1 might act as a ceRNA to sponge miRNA and indirectly regulate Tph2, Slc6a4, Dbh, and Th expression in the EMP-induced delirium-like neuropsychiatric disorders." (PMID 36750928, 2023).
Dyskinesia (1 paper, 2022). A movement disorder which consists of effects including diminished voluntary movements and the presence of involuntary movements. "Carriers of at least one TPH2 rs4290270 A allele and at least one 5-HTTLPR S variant had lower odds for development of dyskinesia (OR = 0.29; 95% CI = 0.09–0.91; p = 0.034)." (PMID 35207756, 2022). "Furthermore, carriers of at least one TPH2 rs7305115 A allele and at least one HTR1A rs6295 C allele had lower odds for MF (OR = 0.20; 95% CI = 0.06–0.71; p = 0.013) as well as dyskinesia (OR = 0.16; 95% CI = 0.04–0.60; p = 0.006)." (PMID 35207756, 2022). "The interaction between TPH2 rs7305115 and 5-HTTLPR showed a protective role in dyskinesia development." (PMID 35207756, 2022).
Dystonia (1 paper, 2023). An abnormally increased muscular tone that causes fixed abnormal postures. "A logical question arises: is the small amount of BH4 that still penetrates the brain enough to increase the TPH2 activity and reduce the expression of dystonia caused by the mutation?" (PMID 37892138, 2023). "Here, the effect of this mutation on hind limbs dystonia, as well as chaperone effects of BH4 on in vitro thermal stability and in vivo activity of mutant TPH2 molecules, was investigated." (PMID 37892138, 2023). "Chronic intraperitoneal administration of 48.3 mg/kg twice per day (or 96.6 mg/kg/day) for 6 and 7 successive days failed to decrease hind-limb dystonia and to increase the TPH2 activity in the brain of Balb/c mice." (PMID 37892138, 2023).
Glucose intolerance (1 paper, 2025). Glucose intolerance (GI) can be defined as dysglycemia that comprises both prediabetes and diabetes. "TPH2-OE mice exhibited glucose intolerance and insulin resistance relative to control mice." (PMID 40455408, 2025).
Hepatic steatosis (1 paper, 2025). Steatosis is a term used to denote lipid accumulation within hepatocytes. "Loss of adipocyte TPH2 protected mice from DIO-induced hepatic steatosis and adipocyte dysfunction." (PMID 40455408, 2025). "Consistent with the reduced hepatic accumulation of TG, HFD-fed mice with adipocyte TPH2 deficiency also had reduced serum ALT and AST levels, indicating protection from hepatic steatosis–induced liver damage." (PMID 40455408, 2025). "In HFD-fed mice, genetic deletion of adipocyte-specific TPH2 reduced both adipose and circulating levels of 5-HT, adipose depot weights, and improved glucose homeostasis and hepatic steatosis, while increasing systemic EE and intestinal energy-harvesting efficiency." (PMID 40455408, 2025). "Taken together, these results underscore that selectively augmenting 5-HT production by TPH2 exclusively in eWAT suppresses BAT thermogenesis and EE, while inducing hepatic steatosis and iWAT lipogenesis, leading to the onset of metabolic abnormalities independent of excess caloric intake." (PMID 40455408, 2025). "Overexpression of eWAT adipocyte TPH2 induces adipocyte dysfunction and hepatic steatosis without HFD feeding." (PMID 40455408, 2025).
Hyperinsulinemia (1 paper, 2025). An increased concentration of insulin in the blood. "In the current study, we demonstrated that obese humans with hyperinsulinemia have increased adipose tissue TPH2 expression." (PMID 40455408, 2025). "Taken together, future studies are needed to further investigate the possible interactions and clinical relevance between hyperinsulinemia-induced adipocyte TPH2 expression, circulating levels of 5-HT, and their effects on systemic metabolism and metabolic disorders." (PMID 40455408, 2025).
Hyperphenylalaninemia (1 paper, 2024). "These mice show reduced levels and activity of PAH, TPH2, and TPH1 in liver, brain, and pineal gland, respectively, and experience hyperphenylalaninemia and central and peripheral serotonin deficiency." (PMID 39695187, 2024).
impulse control disorder (1 paper, 2022). A category of behaviors that can be loosely defined as the failure to resist an impulsive act or behavior that may be harmful to self or others. "Constructed haplotypes of the TPH2 showed increased risk for VH (OR = 1.94; 95% CI = 1.06–3.55; p = 0.032) and impulse control disorders (OR = 5.20; 95% CI = 1.86–14.50; p = 0.002)." (PMID 35207756, 2022).
insomnia (1 paper, 2018). A sleep disorder characterized by difficulty in falling asleep and/or remaining asleep. "Third, only one variant in the TPH-2 gene was genotyped, which prevented further locus-to-locus and gene-to-gene analyses, as it is generally accepted that insomnia is a polygenic disorder." (PMID 29952309, 2018). "Further confirmation of our findings in an independent and large sample of the Chinese population is warranted to clarify the role of the TPH-2 gene polymorphism rs4290270 in insomnia." (PMID 29952309, 2018). "Moreover, as identified by other studies, mutation in the TPH-2 gene rs4290270 was observed to exert a significant impact on TPH-2 mRNA expression in the postmortem human pons, which may, at least in part, sustain the involvement of TPH-2 in neuropsychiatric disorders, including insomnia." (PMID 29952309, 2018).
ischemic stroke (1 paper, 2021). A stroke disorder caused by obstruction of blood flow to the brain, due to thrombotic (local blood clot formation) or embolic (due to a blood clot or other material traveling from another site) event. "Furthermore, we also wished to learn whether changes are detectable in the expression of TPH1, TPH2, IDO1, KYAT1 and AADAT genes in peripheral blood samples (PBS) of ischemic stroke patients during the course of the disease." (PMID 34680558, 2021).
memory impairment (1 paper, 2019). "Because compensation through a 5-HT-dependent mechanism are absent in Tph2-/- mice, resilience to foot shock-mediated memory impairments may be derived directly from absence of 5-HT signaling in the dHip." (PMID 31068767, 2019).
multiple system atrophy (1 paper, 2018). Multiple system atrophy (MSA) is a neurodegenerative disorder characterized by autonomic failure (cardiovascular and/or urinary), parkinsonism, cerebellar impairment and corticospinal signs with a median survival of 6-9 years. "Furthermore, in a study of 12 patients with multiple system atrophy, significant reduction of TPH2 neurons was shown in both the VLM and medullary raphe in those dying suddenly." (PMID 29608654, 2018).
nephritis (1 paper, 2024). Inflammation of renal tissue. "Furthermore, SLE patients with nephritis showed significantly higher percentages of Tph2 cells when compared to patients without nephritis." (PMID 38448723, 2024).
opioid dependence (1 paper, 2021). "The present study reports on the association of 5HTTLPR, STin2, TPH1 (A218T), and TPH2 (G703T) polymorphisms of the serotonergic pathway with self-harm, depressive symptoms, impulsiveness, and aggression in opioid dependence." (PMID 34900485, 2021).
ovarian carcinoma (1 paper, 2022). A malignant neoplasm originating from the surface ovarian epithelium. "Ovarian cancer patients with higher RNA levels of TPH2, DCN, TRHDE, and LUM have lower OS when compared with ovarian cancer patients with lower levels of these genes." (PMID 35008958, 2022). "Following RBPMS knockout, the expression levels of TPH2, DCN, TRHD2, LUM, and SERPINE1 were in agreement with the survival outcomes: The PFS and OS were worse in ovarian cancer patients with higher levels of these transcripts." (PMID 35008958, 2022).
pheochromocytoma (1 paper, 2020). "However, an in vitro study using PC12 cells, a cell line derived from a pheochromocytoma of the rat adrenal medulla, showed that the mutation R441H does not impair TPH2 oligomerization." (PMID 32119710, 2020).
postpartum depression (1 paper, 2024). A type of clinical depression that occurs after childbirth. "Relevant to postpartum depression, single nucleotide polymorphisms (SNPs) in tryptophan hydroxylase 2 gene (TPH2), an enzyme in the rate-limiting step in serotonin synthesis, has been associated with postpartum depression." (PMID 38632592, 2024).
Salmonella Infections (1 paper, 2024). Infections with bacteria of the genus SALMONELLA. "We found that animals treated with the HTR7 antagonist phenocopied the conditional Tph2 KO mice in that they exhibited decreased levels of fecal IgA and increased susceptibility to Salmonella infection." (PMID 39455564, 2024). "Interestingly, we found that Salmonella infection increased intestinal motility in WT mice and that Tph2 KO animals also exhibited a similar increase in gut motility with Salmonella infection." (PMID 39455564, 2024). "Mice treated with the HTR7 antagonist did not display reduced gut motility but showed increased susceptibility to Salmonella infection, suggesting that gut motility is not the only factor that explains the elevated susceptibility to Salmonella infection in Tph2 KO animals." (PMID 39455564, 2024).
sleep disorder (1 paper, 2014). A change from the patient's baseline sleeping pattern, in the hours slept and/or an alteration/dysfunction in the stages of sleep. "In a recent study of pain-induced sleep disorder, similar optical stimulation was used to activate defined 5-HT neurons in the dorsal raphe nucleus (DRN) of TPH2-ChR2 mice in vivo." (PMID 25410898, 2014).
tic disorder (1 paper, 2013). Disorders characterized by recurrent TICS that may interfere with speech and other activities. "Tryptophan hydroxylase-2 (TPH2) is a potential candidate gene for screening tic disorder (TD)." (PMID 23360517, 2013).
Tourette syndrome (1 paper, 2013). A neurologic disorder caused by defective metabolism of the neurotransmitters in the brain. "Several studies have investigated an association between the TPH2 gene and other psychiatric disorders, but only one study to date has demonstrated an association between TPH2 and Tourette’s syndrome (TS)." (PMID 23360517, 2013).
Visual hallucination (1 paper, 2022). Visual perception in the absence of a visual stimulus. "Carriers of the HTR1A rs6295 GC genotype (OR = 2.58; 95% CI = 1.15–5.78; p = 0.021), TPH2 rs4290270 AA genotype (OR = 2.78; 95% CI = 1.08–7.03; p = 0.034), and at least one TPH2 rs4570625 T allele (OR = 1.86; 95% CI = 1.00–3.44; p = 0.047) had increased risk for visual hallucinations (VH)." (PMID 35207756, 2022).